AREG (amphiregulin)
Diseases named in the same sentence as AREG in open-access papers (continued):
Sharing a sentence is not in itself a finding about the gene and the disease.
metastatic colorectal cancer (5 papers, 2016 to 2023). "Using clinical data and a meta-analysis, high AREG and EREG mRNA expression levels were found to be associated with both progression-free and overall survival of patients with metastatic colorectal cancer treated with Cetuximab-based chemotherapy." (PMID 31181806, 2019). "We conducted a meta-analysis of studies that investigated AREG and/or EREG mRNA levels in primary tumors to determine their prognostic value in metastatic colorectal cancer (mCRC)." (PMID 27344184, 2016). "In terms of EREG/AREG as a combined dichotomous biomarker, data from the PICCOLO trial confirmed that high ligand mRNA levels or IHC positivity are predictive biomarkers of benefit from panitumumab treatment in patients with metastatic colorectal cancer." (PMID 37974093, 2023). "When AREG was analyzed separately as a dichotomous variable, the CALGB 80203 and PICCOLO trials showed that AREG mRNA expression and AREG IHC were neither prognostic markers nor predictive markers of benefit from EGFR-targeted therapy in RAS wt metastatic colorectal cancer." (PMID 37974093, 2023).
osteosarcoma (5 papers, 2011 to 2024). A usually aggressive malignant bone-forming mesenchymal neoplasm, predominantly affecting adolescents and young adults. "Overall, we validated that the expression of AREG is associated with osteosarcoma metastasis, signifying that AREG is a novel marker for cancer progression and metastasis of bone sarcomas." (PMID 26503469, 2015). "To understand the role of AREG in osteosarcoma metastasis, in the current study, we examined its expression level and the effect of exogenous AREG treatment in osteosarcoma cells." (PMID 26503469, 2015). "In summary, our findings suggested that AREG promoted cancer cell motility of osteosarcoma and up-regulated the expression of ICAM-1 through the EGFR/PI3K/Akt/NF-κB signaling pathway." (PMID 26503469, 2015). "Next, to understand the effect of AREG on osteosarcoma cells, we first determined the levels of AREG in two human osteosarcoma cell lines (MG63 and U2OS) and in one human fetal osteoblastic cell line (hFOB 1.19)." (PMID 26503469, 2015). "Our study demonstrates that higher expression of AREG promotes the migration of osteosarcoma cells and that AREG supplementation can further enhance migration." (PMID 26503469, 2015). "Immunohistochemistry (IHC) applied for clinical specimens derived from patients with osteosarcoma revealed that the AREG expression level correlated with tumor stage in osteosarcoma." (PMID 26503469, 2015). "To determine the clinical significance of AREG in patients with osteosarcoma, we utilized a tissue microarray for evaluation by IHC to compare the expression of AREG in normal bone and different grades of osteosarcoma." (PMID 26503469, 2015). "In addition, amphiregulin expression has been detected in few other examples of mesenchymal lesions, such as malignant fibrous histiocytoma, osteosarcoma, and fibrous and osseous dysplasia of the jaw." (PMID 34468540, 2021). "However, the effect of AREG on metastasis activity in human osteosarcoma cells has yet to be determined." (PMID 26503469, 2015). "According to the results described thus far, we can hypothesize that elevated levels of AREG in osteosarcoma stimulate cancer cell migration by promoting ICAM-1 expression." (PMID 26503469, 2015). "Finally, we observed that shRNA silencing of AREG decreased osteosarcoma metastasis in vivo." (PMID 26503469, 2015). "Therefore, AREG may be a new molecular therapeutic target for reduction of metastasis in osteosarcoma." (PMID 26503469, 2015). "AREG upregulates ICAM-1 expression via EGFR/PI3K/Akt/NF-κB signaling and promotes the cancer cell viability of osteosarcoma." (PMID 36843929, 2023). "Overall these results imply that AREG and EGFR act through the PI3K/Akt-dependent signaling pathway to enhance ICAM-1 expression and cell migration in human osteosarcoma cells." (PMID 26503469, 2015). "To understand the level of AREG between the normal and the malignant cells, we examined the levels of AREG and ICAM-1 between hFOB 1.19 and osteosarcoma (MG63 and U2OS)." (PMID 26503469, 2015). "Because AREG supplementation can increase EGFR activity, which consequently enhances osteosarcoma cell migration, we speculated whether the PI3K/Akt signaling pathway mediates the AREG-induced cell migration." (PMID 26503469, 2015). "To test whether AREG increased the cell migration of osteosarcoma through EGFR, we reduced the EGFR expression by transfecting EGFR siRNA and found that EGFR siRNA inhibited the AREG-induced cancer cell migration and inhibited the AREG-induced ICAM-1 upregulation of the mRNA level." (PMID 26503469, 2015). "Furthermore, AREG treatment increased the wound-healing activities and cell motility of these cell lines, although it did not affect cellular viability in both human osteosarcoma cell lines (data not shown)." (PMID 26503469, 2015).
bladder cancer (4 papers, 2014 to 2024). "Differentially expressed genes involved in ErbB signalling pathway pointed strong alterations of GAB1 and AREG in the bladder cancer tissues." (PMID 27779188, 2016). "Interestingly, AREG, ATF3, ZFP36, and DUSP1 were all associated with inflammation and cancer, specifically enrichment of adipocytokine signaling, bladder cancer, epithelial cell signaling in Helicobacter pylori infection, and JAK/STAT signaling pathways in patients with high AREG expression." (PMID 35372438, 2022). "PVRL4 was predominantly expressed in BC epithelial cells, AREG was expressed in BC epithelial cells and normal control myeloid cells, and FGFBP1 and WFDC2 were expressed in bladder cancer epithelial cells but not in normal tissue." (PMID 38532419, 2024).
chronic myelogenous leukemia (4 papers, 2019 to 2021). "Exosomes originated from patients with chronic myelogenous leukemia (CML) patients are enriched in amphiregulin (AREG), therefor inducing EGFR signaling in stromal cells." (PMID 33521365, 2021). "In addition to exosomal microRNAs, chronic-myelogenous-leukemia-derived exosomal amphiregulin (AREG) activated Epidermal growth factor receptor (EGFR) and SNAIL expression." (PMID 32252322, 2020). "In addition, in chronic myeloid leukemia model, we have previously shown that AREG is involved in the activation of EGFR downstream signaling in mesenchymal stromal cells leading to the expression and release of IL8." (PMID 30621731, 2019).
diabetes (4 papers, 2021 to 2023). "From this we postulated that amphiregulin promoted islet tissue repair and slowed the progression of diabetes in NOD mice." (PMID 37903947, 2023). "We postulated that amphiregulin promoted islet tissue repair and slowed the progression of diabetes in NOD mice." (PMID 37577652, 2023). "Moreover, Foxp3+ Tregs maintained amphiregulin production at diabetes onset, suggesting that islet-resident Tregs retain the capacity to produce amphiregulin throughout the course of disease." (PMID 37903947, 2023). "To fully determine whether loss of amphiregulin in NOD mice leads to reduced beta cell survival and accelerated diabetes, we monitored female NOD.Areg−/− mice and wild-type littermate controls for the development of spontaneous autoimmune diabetes." (PMID 37903947, 2023). "The similarity in diabetes development between NOD.Areg+/+ and NOD.Areg−/− mice indicates that amphiregulin does not have a role in autoimmune diabetes disease progression." (PMID 37903947, 2023).
glioblastoma (4 papers, 2010 to 2025). The most malignant astrocytic tumor (WHO grade IV). "Significant inverse correlation was also found between SOSCS6 and AREG levels in skin cutaneous melanoma and glioblastoma multiforme." (PMID 25180228, 2014). "In contrast, the non-selective HDACi valproic acid enhanced the secretion of amphiregulin in glioblastoma cells, associated with concomitantly increased resistance to temozolomide, and in a non-malignant context, HDAC inhibition led to amphiregulin induction in oocytes." (PMID 39864337, 2025).
head and neck squamous cell carcinoma (4 papers, 2015 to 2025). A squamous cell carcinoma that arises from any of the following anatomic sites: lip and oral cavity, nasal cavity, paranasal sinuses, pharynx, larynx, and salivary glands. "Similarly, in head and neck squamous cell carcinoma (HNSCC), CAFs promote resistance to EGFR inhibitors through the secretion of Matrix Metalloproteinases (MMPs) and Amphiregulin (AREG)-mediated receptor stabilization." (PMID 40940809, 2025).
helminth infection (4 papers, 2012 to 2020). "Other known genes involved in protective immunity to helminth infection strongly upregulated by infection in CHB included amphiregulin (AREG, 2.2 fold), granzyme genes A and B (GZMA and GZMB, 6.8 and 12.9 fold, respectively)." (PMID 27197554, 2016). "As well as mediating resistance to helminth infection, ILC2s promote tissue repair through the release of amphiregulin and IL-1318 and therefore may contribute to the maintenance of homeostasis in the decidua." (PMID 32764636, 2020). "We showed previously that the epidermal growth factor family member Amphiregulin is expressed by T cell receptor-activated mouse CD4 T cells, particularly Th2 cells, and helps eliminate helminth infection." (PMID 22720031, 2012).
Insulin resistance (4 papers, 2022 to 2025). Increased resistance towards insulin, that is, diminished effectiveness of insulin in reducing blood glucose levels. "Our study found that amphiregulin (AREG) was upregulated when insulin resistance occurred at the early state of T2DM." (PMID 39981678, 2025). "The aim of this study was to evaluate the relationship between insulin resistance and amphiregulin." (PMID 39981678, 2025). "Moreover, after three months follow-up, the serum levels of AREG decreased, accompanied by the alleviation of insulin resistance." (PMID 39981678, 2025). "With regard to the mechanism involved, we proposed the hypothesis that AREG might play a role in insulin resistance partly through AREG-EGFR pathways." (PMID 39981678, 2025). "Similar to Waved 2 mice, global AREG−/− mice were protected against insulin resistance in response to the HFD, as indicated by lower body weight and fasting blood glucose as well as improved glucose tolerance tests and insulin tolerance tests compared to WT mice." (PMID 35948530, 2022). "In this regard, global AREG deletion protected against insulin resistance in response to the HFD, and AREG−/− BMDMs had impaired migration and reduced induction of proinflammatory genes with M1 polarization and greater induction of anti-inflammatory genes with M2 polarization." (PMID 35948530, 2022). "We hypothesized that AREG might play a role in insulin resistance at the early stage in T2DM." (PMID 39981678, 2025). "Amphiregulin is upregulated in obese individuals than in normal size people, whether diabetic or not, and positively correlates with the homeostasis model assessment index, suggesting early signs of insulin resistance and abnormal glucose metabolism." (PMID 39981678, 2025). "In contrast, both EGFR and its ligand, amphiregulin, markedly increased in ATMs in HFD-induced obesity, and selective deletion of EGFR in ATMs reduced HFD-induced obesity, adipose tissue derangements and insulin resistance." (PMID 35948530, 2022). "In conclusion, AREG was upregulated in obese individuals than in normal size people, whether diabetic or not, and was significantly and positively correlated with HOMA-IR, suggesting early signs of insulin resistance and abnormal glucose metabolism." (PMID 39981678, 2025). "But the involvement of AREG in insulin resistance or T2DM has not yet been established." (PMID 39981678, 2025).
liver cirrhosis (4 papers, 2017 to 2024). "Elevated hepatic AREG expression have been described in patients with liver cirrhosis and cholestatic liver disease." (PMID 38571949, 2024). "AREG gene expression was detected in human liver cirrhosis and carbon tetrachloride-induced rat cirrhosis." (PMID 37868614, 2023). "Our results showed no relation between Child-Pugh classification and neither serum DKK1 nor AREG levels in patients with liver cirrhosis or HCC." (PMID 31649806, 2019).
lung diseases (4 papers, 2017 to 2025). "Studies have found that amphiregulin plays an important role in the occurrence and development of lung diseases." (PMID 38394508, 2024). "A previous study has reported that AREG acts as an important mediator in inflammation and the tissue repair process in lung diseases." (PMID 36578010, 2022). "Amphiregulin is an endogenous pro-repair mediator that has been increasingly implicated in the resolution and repair of asthmatic lung disease and nonallergic chronic lung disease." (PMID 29387711, 2017). "Therefore, antifibrotic drugs inhibiting AREG expression may alleviate lung diseases related to IIM." (PMID 40725192, 2025). "AREG levels are significantly elevated in various biological samples from patients with IPF and other pulmonary diseases compared to healthy controls, including circulation, bronchoalveolar lavage fluid, and sputum." (PMID 40725192, 2025).
myopia (4 papers, 2020 to 2025). "Mechanistically, amphiregulin may promote myopia progression by activating the EGFR–ERK–mTORC1 signaling pathway." (PMID 40990868, 2025). "The role of AREG and PDE10A in the pathogenesis of myopia requires further studies in animal models and human genetic epidemiology." (PMID 32269590, 2020). "However, elucidating the role of AREG and PDE10A in the pathogenesis of myopia requires further animal model and human genetic epidemiology studies." (PMID 32269590, 2020).
oral squamous cell carcinoma (4 papers, 2016 to 2024). "In a helicase-independent manner, DDX3 drives expression of amphiregulin (AREG) and the secretory phenotype that stimulates growth of oral squamous cell carcinoma cells in an auto- paracrine mechanism." (PMID 35048066, 2021). "The intracellular signaling pathways controlling epidermal growth factor (EGF)-induced amphiregulin (AREG) expression were examined in three oral squamous cell carcinoma (OSCC) cell lines." (PMID 27669890, 2016). "Impressively, lysates obtained from oral squamous cell carcinoma lines HSC2 and TR146 but also the healthy equivalent, the oral epithelial cells, all provoked the increased expression of STC1, AREG, and C11orf96 in gingival fibroblasts." (PMID 39061769, 2024). "Whereas AREG acts as a tumor promoter for oral squamous cell carcinoma (OSCC) cells, and OSCC tissues have higher AREG mRNA level than normal gingivae, HNSCC patients have lower AREG serum levels than healthy controls." (PMID 27669890, 2016).
pancreatic ductal adenocarcinoma (4 papers, 2016 to 2025). An infiltrating adenocarcinoma that arises from the epithelial cells of the pancreas. "Lastly, cluster #8 (i.e., PP-4) was enriched in inflammatory and EMT-inducing markers, often associated with pancreatitis and pancreatic ductal adenocarcinoma, such as LTB, IL32, and AREG." (PMID 37649117, 2023). "Further, DCA has been shown to induce ectodomain shedding of the EGFR ligand amphiregulin (AREG), which activates EGFR and downstream signaling pathways like MAPK and STAT3, promoting cell cycle progression and tumorigenicity in CRC and pancreatic ductal adenocarcinoma." (PMID 40722646, 2025).
pulmonary hypertension (4 papers, 2022 to 2025). Increased pressure within the pulmonary circulation due to lung or heart disorder. "The key pathogenic features of pulmonary hypertension are endothelial apoptosis and vascular inflammation, which are caused by the down-regulation of Amphiregulin, accompanied by HIF-1a and BAD-mediated up-regulation of the target genes such as RRP1B, PHB2, and NCOA6." (PMID 35732465, 2022). "In a model of pulmonary hypertension, amphiregulin produced by endothelial cells is thought to signal in an autocrine fashion to promote endothelial cell survival and proliferation." (PMID 40100295, 2025). "In pulmonary arterial hypertension, the absence of AREG promotes pulmonary endothelial cell death and affects pulmonary vascular remodeling.Additionally, Tregs also promote muscle regeneration and angiogenesis in ischemic limbs via AREG secretion." (PMID 40495143, 2025).
alopecia (3 papers, 2018 to 2021). Hair loss usually from the scalp. "Furthermore, AREG deficiency in Rhbdf2cub/cub mice prevents the alopecia, sebaceous gland enlargement, and rapid wound‐healing phenotypes, suggesting that AREG is the primary mediator of the Rhbdf2cub phenotype 19." (PMID 29632822, 2018).
breast tumor (3 papers, 2015 to 2019). "Together, our results provide new insight into the function of AREG in mammary gland biology, regulation of PyMT, and breast tumor growth." (PMID 30367629, 2018). "In human breast tumors, HER2/Neu may be overexpressed but is rarely mutated or activated; thus, amphiregulin expression may influence tumor promotion and progression." (PMID 31355130, 2019). "By crossing PyMT mice with AREG-null mice, we have evaluated the properties of the spontaneous PyMT breast tumor model in the absence of AREG." (PMID 30367629, 2018).
Cerebral ischemia (3 papers, 2015 to 2024). Restriction of arterial blood supply to the brain associated with insufficient oxygenation to support the metabolic requirements of the tissue. "AREG (amphiregulin) was another outstanding protein found to have increased levels in CSF after cerebral ischemia." (PMID 29784938, 2018). "We found that the expression levels of amphiregulin and epiregulin were significantly increased under conditions of cerebral ischemia." (PMID 25675253, 2015).
E. coli infection (3 papers, 2016 to 2019). "We further show that pro-AREG is cleaved from the cell surface in response to E. coli infection, which is consistent with a number of studies demonstrating upregulation of AREG transcription as well as increased proteolytic cleavage of pro-AREG in response to various bacterial infections." (PMID 30524196, 2018). "Here, p38 showed a specific phosphorylation after E. coli infection, but a combined treatment with AREG and E. coli failed to reduce the phosphorylation." (PMID 32082070, 2019). "Hence, upon E. coli infection-induced cleavage of pro-AREG, CBMO show an 11-fold higher level of soluble AREG compared to PBMO." (PMID 32082070, 2019).
gastric tumour (3 papers, 2014 to 2017). "Gastric tumours from WP1066- treated mice had reduced polymorphonuclear inflammation, coincident with inhibition of numerous proinflammatory cytokines including IL-11, IL-6 and IL-1β, as well as the growth factors Reg1 and amphiregulin." (PMID 24804649, 2014).
inflammatory bowel disease (3 papers, 2022 to 2025). A spectrum of small and large bowel inflammatory diseases of unknown etiology. "Inflammatory bowel disease: Short-chain fatty acids (SCFAs) such as butyrate regulate the expression of AREG in DCs via the GPR43 and Blimp-1 pathways." (PMID 40002370, 2025).
ischemia (3 papers, 2018 to 2024). A hypoperfusion of the BLOOD through an organ or tissue caused by a PATHOLOGIC CONSTRICTION or obstruction of its BLOOD VESSELS, or an absence of BLOOD CIRCULATION. "Extensions of these findings suggest HIF2A-dependent induction of AREG in cardioprotection from ischemia, and implicate pharmacologic strategies that stabilize HIFs or promote AREG signaling in cardioprotection from ischemia and reperfusion injury." (PMID 29483579, 2018).